MIR3648-2 (microRNA 3648-2)
Synonyms: hsa-mir-3648-2
Gene: MicroRNA gene on chromosome 21 (8,986,999 to 8,987,178, forward strand). Ensembl gene ENSG00000264462.
Gene Ontology:
Biological process: positive regulation of osteoblast differentiation
Homologues: Paralogues in human: MIR3648-1 (100% identical).